ENSG00000252580
Gene: Small nucleolar RNA gene on chromosome 9 (26,796,173 to 26,796,304, reverse strand). Ensembl gene ENSG00000252580.
Homologues: Orthologues: rat LOC120102627 (73% identical). Paralogues in human: SNORA31B (83% identical), SNORA31 (62% identical).